HOXA3 (homeobox A3)
Diseases named in the same sentence as HOXA3 in open-access papers (continued):
Sharing a sentence is not in itself a finding about the gene and the disease.
tumor (24 papers, 2008 to 2025). "To further explore the mechanisms underlying the inhibitory effects of miR-10b on tumor invasion and metastasis, we performed bioinformatics analysis to identify the potential of HOXA3 as one target gene of miR-10b in ccRCC cells." (PMID 30975094, 2019). "Furthermore, several Hox genes (including Hoxa3) have been implicated in controlling the conversion of ECs to the angiogenic phenotype, which is of great relevance for tumor-angiogenesis, as well as for neo-vascularization during wound healing and other normal adult physiological activities." (PMID 18826643, 2008). "Of note, the HOXD10 and HOXA3 homeobox genes showed a hypermethylated DMR with a greater than 0.2 change in the beta value in every tumor tissue type in the present study." (PMID 38886487, 2024). "Both, proapoptotic BCL-2 or MAP kinase pathway members (BIK, BAK1, MAP3K12, and MAPK9) and proliferation-associated tumor drivers (FOS, HOXA3, and POLR2B) had an increased gene expression." (PMID 35778418, 2022). "It was worth noting that we found HOXA13 and HOXA3 were upregulated in tumor samples compared with normal samples." (PMID 35342423, 2022). "Immunofluorescence experiments on tumour tissues formed in nude mice showed that Ki67, a marker for tumour proliferation, and HOXA3 were significantly decreased in the HOXA‐AS2 knockdown group than in the control group." (PMID 33683826, 2021). "HOXA-AS3 has also been identified as a novel target in NSCLC patients owing to its ability to downregulate HOXA3 and to thereby modulate tumor cell resistance to cisplatin treatment." (PMID 33602223, 2021). "To further investigate the relationship between HOXA-AS3 and HOXA3, we performed western blotting and qPCR to detect the expression of HOXA-AS3 or HOXA3 in tumor tissues from nude mice." (PMID 31615976, 2019). "Furthermore, the categorization of samples based on tumor progression revealed that HOXA3 was upregulated in the TN0 samples compared to TN0 + samples, indicating differential expression across the groups." (PMID 40676709, 2025). "Notably, HOXA3 transcriptionally activates aerobic glycolysis, thereby significantly accelerating tumor progression." (PMID 38311789, 2024). "Mechanically, miR-10b targets HOXA3 to exert its tumor-suppressive effect on ccRCC in vitro." (PMID 30975094, 2019). "Of 22 differentially methylated promoters common between all LS tumor groups, seven inversely correlated with expression: ADHFE1, DAPP1, FBLIM1, GRIA4, HOXA3, KLF17, and ZNF528." (PMID 40753397, 2025). "Among the top of the list sorted by the smallest adjusted P values were five genes: ADHFE1, EYA4, FBLIM1, HOXA3, and HOXA5, all hypermethylated in all tumor groups." (PMID 40753397, 2025). "Of those, eight (HOXA3, HOXA5, ATP10A, SOX2, MIR922, ADAMTSL1, KHDRBS2, and LITD1) were hypermethylated in at least one LS tumor group like here in FAP normal, whereas NEDD4L, and FOXP1 were hypermethylated in LS carcinomas and here in LS normal." (PMID 40753397, 2025). "Rui Yang and his team demonstrated that the transcription factor homeobox A3 (HOXA3) promotes aerobic glycolysis in GBM cells by activating the transcription of lysine-specific demethylase KDM6A, thereby promoting tumor growth." (PMID 39493751, 2024). "Of note, except for HOXA3, TWIST1, and ID1, the other seven genes are all proangiogenic genes that can be expressed and secreted by tumor cells, which implied the potential role of ELK4 in tumor angiogenesis in a paracrine manner in CRC." (PMID 37786278, 2023). "HOXA1, HOXA2, HOXA3, and HOXA10 had high expression in GBM tumor tissues compared to normal tissues." (PMID 37351805, 2023). "Previous studies have suggested that HOXB3 functions as a tumor suppressor in RCC and that HOXA3 is a potential target of miR-10b in cell proliferation." (PMID 30975094, 2019). "Accordingly, transcript levels for seven of these genes were evaluated, with five of them (MEIS1, HOXA3, OTX2, TWIST1, and PROM1) being underexpressed in the tumor samples." (PMID 25908946, 2015).
tumor (continued). "In these cases, HOXA-AS2 modulates different miRNA-related pathways, such as miR-509-3p/BTN3A1, miR-15a-5p/HOXA3, miRNA-302c-3p/ZFX, miR-519/HIF-1α/PD-L1, miR-124-3p/E2F3, miR-216a-5p, miR-125b/Smad2, and miR-520d-3p/KIAA1522/IGF2BP3, to promote tumor progression." (PMID 38311789, 2024).
cancer (16 papers, 2009 to 2025). A tumor composed of atypical neoplastic, often pleomorphic cells that invade other tissues. "The expression of HOXA3 is associated with the immune system and cancer development, where it has been used as the diagnostic biomarker in various cancer." (PMID 36106103, 2022). "HoxA3 causes endothelial cells to become more motile and seems to promote angiogenesis, which is lacking in diabetic and aged tissue, although theoretically patients with active cancer should avoid angiogenic factors." (PMID 37337031, 2023). "HOXA3 had ceRNA lncRNAs in ten cancers and showed high correlation coefficients in BRCA, CESC, HNSC and LUSC." (PMID 35721492, 2022). "HOXA-AS2 is a 1048-bp lncRNA located between the HOXA3 and HOXA4 genes in the HOXA cluster that is tightly associated with inflammation-linked cancers." (PMID 34511122, 2021). "However, a main finding from that study was the differential methylation of the HOXA locus, which the current study also reports in the shared hypermethylation of HOXA3 across cancers." (PMID 38886487, 2024). "The reports regarding HOXA3 are controversial across cancers." (PMID 33816499, 2021). "We identified two homeobox genes, HOXA3 and HOXD10, that are hypermethylated in all 16 cancer types." (PMID 38886487, 2024). "Focusing on the statistically significant hypermethylated DMRs overlapping homeobox genes, the set of homeobox genes hypermethylated in all 16 TCGA cancer types were the HOXD10 and HOXA3 genes." (PMID 38886487, 2024). "HOXA3, however, does not have a pervasive presence in the literature across cancer types and thus could potentially be a finding that could be used in a general cancer screening." (PMID 38886487, 2024).
hematological neoplasms (1 paper, 2024). "Furthermore, in MSCs from all hematological neoplasms, we observed an overexpression of HOXA2 and HOXA3 as well as HOXB2-8 genes, which are crucial for hematopoietic cell fates and skeletal development." (PMID 38893194, 2024).
HOXA3 also shares sentences with these, for which no sentence is quoted: acute lymphoblastic leukemia (3 papers); acute myeloid leukemia (1); acute myocardial infarction (1); cardiac diseases (1); clear-cell renal cell carcinoma (1); congenital heart disease (1); gastric cancer (1); psychiatric disorder (1); stenosis (1); thyroid cancer (1); Velopharyngeal insufficiency (1).